ANO1 (anoctamin 1)
Diseases named in the same sentence as ANO1 in open-access papers (continued):
Sharing a sentence is not in itself a finding about the gene and the disease.
glioblastoma (continued). "Our results provide strong evidence for a CaMKIIβ-dependent regulation mechanism of ANO1 surface expression and indicate potential therapeutic targets against ANO1-mediated tumorigenesis in glioblastoma cells." (PMID 32357567, 2020). "As we found that 14-3-3γ enhances the surface expression of ANO1 in heterologous expression systems, we next investigated the effect of 14-3-3γ depletion on cell surface expression of endogenous ANO1 in glioblastoma cells." (PMID 27212225, 2016). "Gene silencing of 14-3-3γ and/or ANO1 demonstrated that suppression of ANO1 surface expression inhibited migration and invasion of glioblastoma cells." (PMID 27212225, 2016). "Western blot analysis demonstrated protein expressions of ANO1 and 14-3-3γ in three glioblastoma cell lines, mouse primary astrocytes, and IM-PHFA cells, an immortalized human adult astrocyte cell line." (PMID 27212225, 2016). "Because most ion channels act at the plasma membrane, clarifying the trafficking mechanisms of ANO1 channels at the plasma membrane is important for developing potent therapeutic approaches for glioblastomas." (PMID 27212225, 2016). "Taken together, these results strongly suggest that suppression of ANO1 surface expression inhibits cancer progression of human glioblastoma cells." (PMID 27212225, 2016). "Suppression of ANO1 surface expression using 14-3-3γ-specific short hairpin RNA (shRNA) reduced ANO1-mediated channel activity in glioblastoma such as U251, T98G and U138 cell lines." (PMID 27212225, 2016). "Compared to mouse primary astrocytes or IM-PHFA cells, high level of ANO1 expression was detected in the three glioblastoma cell lines (U251, T98G and U138)." (PMID 27212225, 2016). "For instance, ANO1 is overexpressed in various cancer cells including glioblastoma." (PMID 36935741, 2023). "In addition, specific gene silencing of CaMKIIβ and/or ANO1 suppressed the migration and invasion of glioblastoma cells." (PMID 32357567, 2020). "In addition, we have shown that knockdown of CaMKIIβ reduces the surface expression and channel activity of ANO1 in U251 glioblastoma cells, demonstrating the oncogenic roles of CaMKIIβ-mediated ANO1 surface expression in U251 and U87 MG glioblastoma cells." (PMID 32357567, 2020). "Eventually, this finding may advance research into efficient therapeutic targets for various ANO1-mediated cancers, including glioblastoma." (PMID 32357567, 2020). "Moreover, gene silencing of CaMKIIβ or ANO1 prominently reduced the migration and invasion of U251 and U87 MG glioblastoma cells." (PMID 32357567, 2020). "Phospho-serine binding protein 14-3-3 directly interacts with ANO1 and also stabilizes ANO1 on cell surface by unknown mechanism, both in heterologous models and in glioblastoma U251 cells." (PMID 33250781, 2020). "We also reported that the surface expression of ANO1 was increased by interaction with 14-3-3γ in several glioblastoma cell lines, and ANO1 surface expression is critical for the migration and invasion of glioblastoma cells." (PMID 32357567, 2020). "In addition to numerous human cancer tissues, a previous report showed that ANO1 is highly expressed in glioblastoma cells." (PMID 27212225, 2016). "In addition, gene silencing of 14-3-3γ and/or ANO1 inhibited migration and invasion of these glioblastoma cell lines." (PMID 27212225, 2016). "Furthermore, we demonstrated oncogenic roles of 14-3-3γ-mediated ANO1 surface expression in U251 glioblastoma cells." (PMID 27212225, 2016). "As ANO1 is activated by intracellular Ca2+, it is plausible that receptor-mediated increases in intracellular Ca2+ can activate ANO1 channels, which might promote ANO1-mediated cancer progression of glioblastoma cells." (PMID 27212225, 2016).
glioblastoma (continued). "Therefore, these putative interacting proteins for ANO1 are useful for understanding the regulatory network of ANO1 in glioblastoma cells, although the detailed functions of each interaction should be examined in the ANO1-mediated cancer progression of glioblastoma cells." (PMID 32357567, 2020). "RT-PCR data showed that various ANO1 isoforms could be expressed in these glioblastoma cells." (PMID 27212225, 2016). "Because ANO1-mediated currents were reduced by depletion of 14-3-3γ in U251, T98G, and U138 glioblastoma cells, we examined whether gene silencing by adenovirus containing the shRNA against 14-3-3γ or ANO1 affect characteristics of cancer cells, such as migration and invasion." (PMID 27212225, 2016). "Finally, this finding may help the development of effective therapeutic targets for various ANO1-mediated cancers, including glioblastoma." (PMID 27212225, 2016). "In conclusion, our finding of the regulation of ANO1 surface expression by 14-3-3γ binding establishes a new role for segment a of ANO1 and indicates that 14-3-3γ-mediated ANO1 surface expression has an important role in the cancerous progression of glioblastoma cells." (PMID 27212225, 2016). "However, the regulation of ANO1 surface expression in glioblastoma cells is largely unknown." (PMID 32357567, 2020). "Additionally, studies show that 14-3-3γ enhances the surface expression of ANO1, a calcium-activated chloride channel; silencing ANO1 inhibits glioblastoma cell migration and invasion." (PMID 40896335, 2025). "Cell surface expression of ANO1 is also promoted by Ca2+/Calmodulin-dependent protein kinase II (CaMKII) in heterologous models and in glioblastoma U251 cells, potentially (but not proven) through phosphorylation of ANO1 by CAMKII." (PMID 33250781, 2020). "Although our previous study showed that tumorigenesis of glioblastoma cells was suppressed by inhibition of ANO1, the effect of CaMKII on the activity of ANO1 has never been studied in glioblastoma cells." (PMID 32357567, 2020). "We also measured ANO1 shRNA-1-sensitive Cl− currents in two other glioblastoma cells, T98G and U138 (data not shown)." (PMID 27212225, 2016). "However, we can exclude the involvement of CaMKIIγ in the inhibitory effect of KN-93 on ANO1 currents and the migration of U251 cells, as CaMKIIγ was not expressed in U251 glioblastoma cells." (PMID 32357567, 2020). "Interestingly, we noted that in U251 glioblastoma cells, CaMKIIβ and not CaMKIIγ are involved in the increase of ANO1 surface expression and ANO1 channel activity." (PMID 32357567, 2020).
lung adenocarcinoma (14 papers, 2015 to 2025). A carcinoma that arises from the lung and is characterized by the presence of malignant glandular epithelial cells. "Silencing ANO1 significantly slowed down the growth of lung adenocarcinoma GCL82 and lung squamous carcinoma NCI-H520 cells." (PMID 26305547, 2015). "The analysis of immunohistochemical staining revealed that ANO1 protein expression was positive in 34 of 44 (77.3%) human lung adenocarcinoma tissue samples." (PMID 26305547, 2015). "In this study, our histochemical staining of human samples in this study reveals that 77.3% of lung adenocarcinoma tissues are highly overexpressed with ANO1, whereas only 15% lung squamous cell carcinoma samples show ANO1 positive in the staining." (PMID 26305547, 2015). "ANO1 protein is overexpressed in 77.3% cases of human lung adenocarcinoma tissues detected by immunohistochemistry." (PMID 26305547, 2015). "Western blotting revealed that endogenous ANO1 is expressed at high levels in PC3 and CFPAC-1 (human pancreatic ductal adenocarcinoma derived) cells but not in A549 (human lung adenocarcinoma derived) cells." (PMID 26196390, 2015).
melanoma (14 papers, 2013 to 2025). A malignant, usually aggressive tumor composed of atypical, neoplastic melanocytes. "Here, we report that TMEM16A/ANO1 is significantly up-regulated in A375 human malignant melanoma cells, which carry the BRAF(V600E) mutation." (PMID 39070550, 2024). "Patients harboring ANO1 amplification/hyperexpression displayed significantly shortened irPFS/irOS, which was observed in other retrospective GI cancer cohorts and a melanoma cohort." (PMID 37341301, 2023). "Frequent loss of 9p21 region is a well characterized copy number aberration in melanomas, however, it has not been mentioned as a trans- regulatory element for Anoctamin 1 gene (11q13.3) so far." (PMID 23383013, 2013). "In the RNA sequencing‐based melanoma GSE78220 dataset, ANO1 expression was evidently higher in nonresponders than in responders while also predicted unfavorable trend of irOS." (PMID 37341301, 2023).
hepatocellular carcinoma (12 papers, 2012 to 2023). A malignant tumor that arises from hepatocytes. "Knockdown of ANO1 greatly reduced ERK1/2 phosphorylation in human hepatoma cell line SMMC-7721 under standard growth conditions." (PMID 33250781, 2020). "Similarly, silencing ANO1 in SMMC-7721 hepatoma cell line reduced phosphorylation of p38 (but not JNK) under growth conditions." (PMID 33250781, 2020).
oral cancer (12 papers, 2014 to 2024). "Anoctamin 1 (ANO1), a drug target for various cancers, including prostate and oral cancers, is an intracellular calcium-activated chloride ion channel that plays various physiopathological roles, especially in the induction of cancer growth and metastasis." (PMID 37274097, 2023). "In the present study, we investigated the possible medicinal effects of phytochemicals obtained from S. sphenanthera occuring owing to the inhibition of ANO1, and the physiological effects of schisandrathera D on prostate and oral cancer cells." (PMID 37274097, 2023). "Schisandrathera D decreased the viability of prostate and oral cancer cells and exerted its anticancer effects by activating apoptosis via the reduction of ANO1 protein levels." (PMID 37274097, 2023). "Taken together, our results strongly suggest that Ani-D2 exhibits cytotoxicity in prostate and oral cancer cells by at least partially inducing apoptosis through inhibition of ANO1." (PMID 32899792, 2020). "The cell proliferation, metastasis, and invasion of prostate and oral cancer cells were significantly reduced by the inhibition of ANO1 channel function and reduction of ANO1 protein level." (PMID 32899792, 2020). "Thus, this study highlights that schisandrathera D, which reduces ANO1 protein levels, has apoptosis-mediated anticancer effects in prostate and oral cancers, and thus, can be further developed into an anticancer agent." (PMID 37274097, 2023). "Because of the cancer-related increase in its expression, ANO1 is also known by different names, such as DOG-1 (discovered on gastrointestinal stromal tumors protein 1), ORAOV2 (oral cancer overexpressed 2), and TAOS2 (tumor-amplified and overexpressed sequence 2)." (PMID 32357567, 2020). "ANO1 is also known as transmembrane protein 16A (TMEM16A), gastrointestinal mesenchymal stromal tumour 1 (DOG1), oral cancer overexpressed 2 (ORAOV2), and tumour‐amplified and overexpressed 2 (TAOS2)." (PMID 38685684, 2024). "ANO1 was also known as discovered on GIST-1 (DOG1), tumor amplified and overexpressed sequence 2 (TAOS2), and oral cancer overexpressed 2 (ORAOV2)." (PMID 26196390, 2015). "Thus, we analyzed the expression of ANO1 in OSCC samples and defined its functions in human oral cancer cell line." (PMID 24316695, 2014). "We have shown that ANO1 expression was found in a large majority (132 out 160, 82.5%) of oral cancer tissue, but not in normal tissue and its expression level was higher in metastatic tumors than in non-metastatic tumors." (PMID 24316695, 2014).
Renal cyst (12 papers, 2020 to 2025). A fluid filled sac in the kidney. "Oxidative damage, as measured by lipid peroxidation, has been shown to be greatly elevated in the cystic kidney, and to drive renal cyst growth by activating the anoctamin 1 (ANO1)." (PMID 39000280, 2024). "Moreover, transmembrane member 16A anoctamin 1 (TMEM16A) is a Ca+2-activated Cl− channel that is essential for fluid secretion into renal cysts in vitro." (PMID 40136708, 2025). "Activation of ANO1 by lipid peroxidation drives the proliferation and expansion of renal cysts." (PMID 39000280, 2024). "(iii) Treatment of mice with the ANO inhibitors niclosamide, benzbromarone or Ani9, a more specific inhibitor of ANO1, was highly effective in reducing renal cyst growth and did not cause any obvious side effects." (PMID 38233410, 2024). "Indeed, increased expression of ANO1 (3.7×) was observed in our PKD1 renal cysts." (PMID 39000280, 2024).
squamous cell carcinoma (12 papers, 2010 to 2024). A carcinoma arising from squamous epithelial cells. "In the first cohort of biopsy specimens, ANO1 expression was detected in 3 out of 11 pathologically confirmed squamous carcinomas." (PMID 27016410, 2016). "Convincingly, downregulation of ANO1 expression by siRNA knockdown in SCC-25 (squamous cell carcinoma) cells that express a higher level of ANO1 than HEp-2 had the opposite effect." (PMID 24639373, 2014). "To study the effects of silencing endogenous ANO1 on cell migration, we used SCC-25 squamous cell carcinoma cells that express a higher level of ANO1 than HEp-2." (PMID 20664600, 2010). "Conversely, analysis of squamous cell carcinoma [including human papillomavirus (HPV)-positive] samples from two datasets suggested a positive correlation of ANO1 expression with methylation of two CpG islands on ANO1 gene." (PMID 33250781, 2020). "ANO1 protein was highly expressed in adenocarcinoma of lung, whereas tissues from benign alveoli adjacent to carcinoma and squamous cell carcinoma showed negative staining of ANO1." (PMID 26305547, 2015).
colon cancer (11 papers, 2013 to 2024). "The epidermal growth factor receptor/extracellular signal-regulated kinase signal pathway activation influences the onset and progression of colon cancer by upregulating the expression level of ANO1 in colon cancer." (PMID 36518255, 2022). "In colon cancer HT-29 cells, silencing ANO1 resulted in significant increase of the cell number at G1 phase and a decrease of the cell number at S phase." (PMID 27732935, 2016). "To further confirm the effect of ANO1 on proliferation, we selected two colon cancer cell lines, HCT116 and HT-29, and observed the colony formation in soft agar after ANO1 silencing." (PMID 27732935, 2016). "The expression of cyclin A2, CDK1 and CDK2 in colon cancer HT-29 cells was decreased upon the knockdown of ANO1." (PMID 27732935, 2016). "ANO1 knockdown was performed for mouse colon cancer (COAD) cell lines." (PMID 37341301, 2023). "In the HNSCC cell line UM-SCC1 and colon cancer SW620 cells, ANO1 promotes cell proliferation by activating MAPK signaling for progression of cell cycle." (PMID 27732935, 2016). "Research data indicate that Fn promotes ANO1 expression in colon cancer cells and that the OXA- and 5-FU-induced apoptosis could be prevented by ANO1." (PMID 35800370, 2022). "In the same study, the authors demonstrated that pharmacological inhibition of ANO1 resulted in cancer cell death, however the role of ANO1 in colon cancer progression has not been examined." (PMID 23372686, 2013). "The two cohorts' top 100 differentially expressed genes (based on survival status) were compared, revealing that ANO1 and SQLE are the two genes commonly differentially expressed between those TAZ-AXL-CTGF-high colon cancer patients who are still alive and those who are deceased." (PMID 23372686, 2013). "Furthermore, ANO1 and SQLE overexpression may further define a poorer prognosis for colon cancer patients overexpressing TAZ-AXL-CTGF." (PMID 23372686, 2013). "Importantly, we also identified two potential therapeutic targets, ANO1 and SQLE, for patients with upregulated TAZ-AXL-CTGF expression; downregulation of either of these two genes may greatly improve the survival of TAZ-AXL-CTGF-high colon cancer patients." (PMID 23372686, 2013). "When both ANO1 and SQLE genes were included in multivariate Cox-regression analysis, we found that mRNA expression of ANO1, but not SQLE, was an independent predictor of patient survival together with both tumor stage and TAZ-AXL-CTGF expression in both colon cancer patient datasets." (PMID 23372686, 2013).
esophageal cancer (11 papers, 2014 to 2024). A primary or metastatic malignant neoplasm involving the esophagus. "In addition, ANO1, is also an esophageal cancer marker, which is especially important in EA patients who are susceptible to esophageal squamous cell carcinoma development." (PMID 31850292, 2019). "Anoctamin 1 (ANO1) has been recently identified to be overexpressed in esophageal carcinomas." (PMID 27016410, 2016). "Thus, ANO1 could potentially be used as a molecular marker for a malignant EA prognosis, EoE symptom monitoring, and esophageal cancer prognosis." (PMID 31850292, 2019).
lymph node metastasis (11 papers, 2015 to 2025). "These genes are negatively correlated with ANO1 and are linked to vascular invasion or lymph node metastasis." (PMID 40396170, 2025). "Multiple Cox proportional hazards regression analysis indicated that lymph node metastasis and ANO1 expression were independent prognostic factors for ESCC patients (hazard ratio = 1.8234 and 1.9031, P = 0.0146 and 0.0020)." (PMID 27016410, 2016). "Univariate Cox proportional hazards regression analysis showed that lymph node metastasis, advanced tumor stages and ANO1 expression were significantly correlated with poorer OS (P = 0.0012, 0.0438 and 0.0018)." (PMID 27016410, 2016). "In some reports, loss of ANO1 was associated with increased EMT and lymph node metastasis." (PMID 29416639, 2018). "However, there was no close association between ANO1 expression and variable clinicopathological factors related with the prognosis of BCA patients, such as TNM stage, lymph node metastasis, histologic grade, and the expression of ER, PR, and HER2." (PMID 29416639, 2018).
bladder cancer (10 papers, 2012 to 2022). "In contrast, Ano1 was expressed in a remarkable fraction of 11q13-amplified breast (4 out of 11) and bladder cancers (6 out of 14), indicating a correlation between amplification of 11q13 and Ano1 protein in these two types of cancer." (PMID 22912841, 2012). "The activation of MAPK/ERK1/2 signaling pathway was demonstrated to enhance the growth of epithelial cancer cells, in particular, bladder cancer and HNSCC, which explains why the ANO1 mutant has lost the proliferating effect." (PMID 24639373, 2014). "It was found that regulators of cell cycle and cell proliferation such as S100A4, CCND2, C13ORF15 (RGCC), and SYK and genes associated with glucose or ion transport such as SLC2A3 and TMEM16A (ANO1) were upregulated in the persistently infected bladder cancer cells." (PMID 34044804, 2021). "UM-SCC1 (a HNSCC cell line) harbors 11q13 amplification and overexpresses ANO1 while T24 (a bladder cancer cell line) does not." (PMID 24639373, 2014). "Supporting this argument, the Duvvuri group, with T24 (a bladder cancer cell line) which does not harbor the 11q13 amplification, also suggested that the role of ANO1 in proliferation may not require the expression of other genes within the 11q13 amplified core region." (PMID 24639373, 2014). "To that end, we constructed a small TMA from available Ano1 protein expressing non-HNSCC tumors from the multi tumor TMA and from 11q13 amplified breast and bladder cancers from previous studies." (PMID 22912841, 2012).
polycystic kidney disease (10 papers, 2015 to 2024). A usually autosomal dominant and less frequently autosomal recessive genetic disorder characterized by the presence of numerous cysts in the kidneys leading to end-stage renal failure. "Finally, polycystic kidneys are under constant oxidative stress, which causes lipid peroxidation and the activation of ANO1 and ANO6." (PMID 37686084, 2023). "We reported earlier an upregulation of the Ca2+ activated chloride channel TMEM16A (anoctamin 1) in polycystic kidney disease." (PMID 32185407, 2020). "Moreover, in mice suffering from polycystic kidney disease, ANO1 expression and Ca2+ signals were found to be upregulated, and both was reversed with knockout of ANO153." (PMID 38233410, 2024).